MTOR (mechanistic target of rapamycin kinase)
Diseases named in the same sentence as MTOR in open-access papers (continued):
Sharing a sentence is not in itself a finding about the gene and the disease.
leukemia (continued). "JAK1/2 inhibitor inactivated the mTOR/p70S6K/4EBP1 pathway and reduced the inhibitory phosphorylation of GSK3 in leukemia cell line, which correlated with JAK1/2 inhibitor reduction of proliferation and survival of these cells." (PMID 26275051, 2015). "In support to this, inhibition of the PI3K/Akt/mTOR pathway by NVP-BEZ235 potentiates effects of vincristine and reduces chemoresistance in in vitro and in vivo leukemia and sarcoma models." (PMID 24930764, 2014). "The aim of our study was to determine mTOR activity in childhood ALL cells (cell lines, and leukemia cells isolated at diagnosis and during treatment)." (PMID 23573198, 2013). "Our laboratory and others have demonstrated that significant functional cross-talk between AMPK, mTOR, IGF-1R/IRS-1, and Akt signaling factors occur in leukemia cells." (PMID 20863384, 2010). "Targeted inhibitors: Efforts to optimize CDK4/CDK6 blockade (e.g., combination regimens or PROTACs), PI3K/AKT/mTOR inhibition (rapalogues in trials), BH3 mimetics such as venetoclax, and menin inhibitors for KMT2A-rearranged leukemias, several of which have shown promising clinical activity." (PMID 41009342, 2025). "The phosphatidylinositol 3‐kinase/Protein Kinase B/mammalian target of rapamycin (PI3K/AKT/mTOR) signalling pathway is pivotal in various cancers, including T‐cell acute lymphoblastic leukaemia (T‐ALL), a particularly aggressive type of leukaemia." (PMID 39542458, 2025). "TSLP may promote leukemia cell proliferation through several signaling pathways, including JAK-STAT, PI3K/mTOR, and MAPK, as well as through other factors such as RAS, IGF1R, and FGFR1." (PMID 40787610, 2025). "Additionally, YW3-56 inhibited the downstream mTOR signaling cascade, resulting in the activation of caspase-3/PARP-dependent apoptosis and a pronounced suppression of leukemia cell proliferation." (PMID 41304891, 2025). "Elevated level and activity of LDHA is observed in K562/MDR leukaemia cells, and oxamate (an LDHA inhibitor) not only inhibits glycolytic flux but also restores the sensitivity of K562/MDR cells to adriamycin by counteracting Akt/mTOR/c-Myc signaling." (PMID 40612109, 2025). "In cases of leukemia, O2•− functions as a messenger for activation signals, initiating crucial signaling pathways such as the mitogen-activated protein kinase (MAPK) and mammalian target of rapamycin (mTOR) upstream pathways." (PMID 37469162, 2024). "Preclinical investigations have shown that inhibitors directed against the phosphoinositide 3-kinase/protein kinase B/mammalian target of rapamycin (PI3K/AKT/mTOR) signaling pathway can bolster the proliferative capacity, persistence, and anti-neoplastic potency of CAR-Ts in leukemia model systems." (PMID 39329777, 2024). "In human leukemia cells (HL-60) and Chinese hamster ovary cells (CHO), ceramide-activated protein phosphatases (Cer-CAPPs) were found to exert inhibitory effects on the Akt-mTOR pathway, promoting autophagy and inducing autophagy-mediated cell death." (PMID 38673870, 2024). "The surviving AML blasts uniquely rewired their profiles, characterized by increased activity of AKT and mTOR pathways, upregulation of YTHDF2, a transcription factor regulating RNA metabolism and counteracting apoptosis of leukemia cells, and increased expression of CD47 and HLA-ABC." (PMID 37386016, 2023). "Since inhibiting the Akt-mTOR pathway can trigger autophagy activation and control HSC homeostasis, thus this network is essential for self-renewal, survival, differentiation, and preventing HSCs from becoming leukemia stem cells (LSCs)." (PMID 37180758, 2023). "Based on our experimental results, we conclude that quercetin has anti-leukemia function, and may induce apoptosis and autophagy of HL-60 cells through modulating the CaMKKβ/AMPK/ mTOR signaling pathway." (PMID 36148953, 2022).
leukemia (continued). "For example, punicalagin exerts the cytotoxic effect by suppressing proliferation and promoting apoptosis and autophagy by activating the caspase cascade, altering Bax and Bcl-2, and regulating autophagy via mTOR/ULK1 signaling in human NB4 and MOLT-4 leukemia cell lines." (PMID 35745713, 2022). "Taken together, we demonstrated that Parkin and USP30 might regulate the AKT/mTOR signaling and cell survival during mitophagy, suggesting USP30 may serve as a potential drug target for leukemia treatment." (PMID 35250566, 2022). "Among these signal pathways, the PI3K/Akt/mTOR signaling pathway has been reported to be aberrantly hyperactivated in multiple cancers such as AML, which is required to sustain the oncogenic potential of leukemia stem cell populations." (PMID 35615374, 2022). "Several PI3K/AKT/MTOR pathway genes were identified to affect cell proliferation in the shRNA screen (e.g. PIK3CD, AKT2, AKT1, RPS6) confirming our previous data about PI3K/AKT/MTOR activation in mouse E2A-PBX1+ leukemia cells." (PMID 35794338, 2022). "Each component represents multiple points that are targetable aspects in leukemia treatment and drugs such as ruxolinib for JAK/STAT inhibition and everolimus for mammalian targeting of rapamycin (mTOR) inhibition are in clinical trials to determine their utility in pediatric ALL." (PMID 34830969, 2021). "In addition overactivation of three signaling oxidative stress pathways, PI3K/AKT/mTOR, MEK/ERK, and JAK/STAT, and oncogenes such as BCR/ABL and RAS are related to the changes in redox homeostasis in leukemia cells and increases in ROS levels." (PMID 34067520, 2021). "PI3K/AKT/mTOR, MAPK kinase (MEK)/extracellular signal-regulated kinase (ERK), and JAK/STAT are the major signaling pathways of oxidative stress and are also the representative signaling pathways for abnormal activation of leukemia cells." (PMID 34067520, 2021). "Pharmacologic inhibition of PI3K signalling exerted pronounced anti-proliferative effects and induced apoptosis in pre-clinical models using leukemia cell lines or primary leukemia samples, but identified limitations of selectively targeting single nodes within the PI3K/Akt/mTOR cascade." (PMID 32993794, 2020). "In the present study, we determined that NTS induced leukemia cell death in vivo through mTOR ubiquitination and degradation and did so without obvious side effects." (PMID 32131492, 2020). "By examining IL-17 signaling-related genes, IL-8, CCL2 levels, mTOR signaling and EIF2 signaling pathways genes, it is confirmed that BMSCs and leukemia cells both contribute to the creation of a competitive niche more favorable for leukemia stem cells." (PMID 33146708, 2020). "If NTS could regulate MUL1 or RNF126 activity at the same time, NTS will be a strong therapeutic tool for leukemia therapy compared to other drugs (e.g., Imatinib) through AKT or mTOR ubiquitination." (PMID 32131492, 2020). "Here, the authors show that CDK8, independent of its kinase activity, regulates mTOR signalling for the maintenance of BCR-ABL1+ leukemia, and that the dual inhibition of CDK8 and mTOR signalling induces apoptosis in these cells." (PMID 31628323, 2019). "Another study involving leukemia cells showed that BMAs activated AMP activated protein kinase (AMPK)-dependent cytoprotective autophagy and downregulated Akt/mechanistic target of rapamycin (mTOR) signaling in the starvation condition." (PMID 30013512, 2018). "In this study, we show that the anti-leukemia effect of dasatinib is enhanced by the TOR-KIs compound AZD2014 at doses that do not fully block mTOR activity as a single agent and preserve normal bone marrow cell proliferation." (PMID 29464092, 2018).
leukemia (continued). "So, the scenario of a continuous metabolic loop, in which VEGF acts on VEGFR2 to activate PI3K/Akt/mTOR pathway that will induce the expression of both MCT1, driving the metabolic fitness, and VEGF that will perpetuate the metabolic adaptation of leukemia cells, can be a possibility." (PMID 29137304, 2017). "It has been shown that polystyrene NPs surface-functionalized with amino groups, but not those with carboxyl groups, obstruct the mTOR signaling in leukemia cells." (PMID 29167516, 2017). "Reflecting the importance of PI3K/AKT/mTOR signaling cascade in many cellular tasks, several PI3K/AKT/mTOR-regulated processes, including cell adhesion and DNA damage response, are also affected in E/R-positive leukemia." (PMID 28418909, 2017). "Taken together, our results demonstrate for the first time that caffeine affects the biological responses of human myeloid cells, including leukaemia cell lines, primary AML cells and primary human basophils by downregulating the mTOR pathway and differentially inhibiting XOD." (PMID 26384306, 2015). "Given our results of hyperactivated mTOR signaling in TTLshort leukemia, mTOR and PI3K signaling activities were addressed in response to pathway inhibition using the prototypic allosteric mTOR inhibitor rapamaycin and the dual mTOR/PI3K inhibitor NVP-BEZ235." (PMID 25682198, 2015). "The mammalian target of rapamycin (mTOR) and phosphoinositide-3-kinase (PI3K) pathways are often aberrantly activated in acute myeloid leukemia (AML) and play critical roles in proliferation and survival of leukemia cells." (PMID 25823922, 2015). "To date, none of the next-generation PI3K/mTOR pathway inhibitors has been evaluated specifically in children, although preclinical studies of many of these drugs are ongoing in childhood leukemias with the goal of swift clinical translation." (PMID 24904824, 2014). "Our data and leukemia mouse model indicate that inhibition of both mTORC2 and HSP90 will produce a synergistic antitumor effect which is more superior to the inhibition of the mTOR or chaperon pathway alone." (PMID 25243120, 2014). "Furthermore, the inhibition of mTOR kinases by PP242 or of Bcr-Abl by imatinib leads to CML cell death, revealing the significance of translation regulation in the pathogenesis of leukaemia." (PMID 25392452, 2014). "In this report, we use two small molecule inhibitors, PP242 (dual mTOR (mammalian target of rapamycin) kinase inhibitor) and hippuristanol (eIF4A inhibitor), to define IRES regulation via a Bcr-Abl–mTOR–eIF4A axis in CML cell lines and primary patient leukaemias." (PMID 25392452, 2014). "Combining PI3K/mTOR and TKI inhibition may prove an effective novel therapeutic strategy in TKI-resistant BCR-ABL1 positive leukemia." (PMID 24349524, 2013). "Taken together, these results suggest that MDM2 may be a therapeutic target to increase TKI-mediated apoptosis and that combining PI3K/mTOR inhibitor and TKI may prove an effective novel therapeutic strategy in TKI-resistant BCR-ABL1 positive leukemia." (PMID 24349524, 2013). "Furthermore, it has been demonstrated that the activation of the PI3K/Akt/mTOR axis is a common feature in patients with AML, and inhibition of mTOR blocks the phosphorylation of this kinase and results in cell death in leukemia progenitor cells." (PMID 24137178, 2013). "In recently published work, we examined the effects of dual TORC1/2 inhibition on various elements of the mTOR pathway in different AML cell lines and primary leukemia blasts from AML patients and compared them to the effects of the classic mTOR inhibitor rapamycin." (PMID 21680954, 2011). "Such potent effects were associated with decreased cell proliferation and survival of leukemia cells and suppressed leukemic progenitor clonogenicity, raising the prospect of using such pan P13’K/AKT/mTOR inhibitors as a potential future approach for the treatment of AML." (PMID 21680954, 2011).
leukemia (continued). "Studies showed that PI3K/Akt/mTOR and MAPK and FAK signaling pathways and their downstream partners were activated in leukemia, inducing the decontrolled proliferation and enhancing the invasiveness of leukemia cells." (PMID 19115995, 2008). "To investigate, in vitro, the regulatory effects of tumor-suppressing gene PTEN on mTOR (mammalian target of rapamycin) signaling pathway, the effects of transfected PTEN and rapamycin on the growth inhibition, and apoptosis induction for human leukemia cell line K562 cells." (PMID 19115995, 2008). "Epicatechin and scopoletin induce apoptosis in leukemia (Jurkat, WEHI-3b) and lung adenocarcinoma (A549) through caspase-3/8 activation, G0/G1 arrest, and downregulation of tumor proliferation genes (EGFR, MDM2, RAF1, mTOR), while enhancing immune responses and reducing COX-2 expression." (PMID 41346617, 2025). "This resistance can be reversed with ferroptosis-mediated inhibition of the AKT/mechanistic target of rapamycin (mTOR) pathway; thus, modulation of the iron homeostasis/ROS/AKT/mTOR pathway may be a potential strategy for the treatment of drug-resistant leukaemia." (PMID 37344500, 2023). "The author concluded that rapamycin effectively eliminates leukemia blast but fails to inhibit mTOR in leukemia stem cells, which could contribute to the limited clinical efficacy of rapamycin in T-ALL." (PMID 37628917, 2023). "We have previously reported that TQ exerted anti-leukemia effects by inducing antiproliferative effects and enhancing apoptosis in MV4-11 AML cells and K562 CML cells and through hypomethylation of JAK/STAT and PI3K/Akt/mTOR-negative regulator genes in MV4-11 AML cells." (PMID 36145344, 2022). "Notably, PI3K/Akt/mTOR network up-regulation has been detected in leukemia stem cells (LSCs) transplanted in non-obese diabetic/severe combined immunodeficiency (NOD/SCID) mice, where it exerted a powerful pro-survival effect." (PMID 32993794, 2020). "The fungal metabolite DN exerts its effects against A3 leukemia cells by decreasing their viability, altering plasma membrane permeability, promoting autophagic morphological changes, arresting the cell cycle at the G1/S phase via p21, p27, TGF-β, and the PI3K/Akt/mTOR pathways." (PMID 33178020, 2020). "Mechanistically, genetic perturbation of CARM1 in the context of leukemia impairs cell-cycle progression, promotes myeloid differentiation, and ultimately induces apoptosis, probably by targeting pathways of proliferation and cell-cycle progression, that is, E2F-, MYC-, and mTOR-regulated processes." (PMID 31657716, 2019). "We hypothesized that addition of a mammalian target of rapamycin (mTOR) kinase inhibitor (TOR-KI) could prevent this resistance and further decrease overall leukemia burden, as TOR-KIs suppress proliferation and survival signals downstream of both the oncogene and extracellular inputs." (PMID 29464092, 2018). "Besides miRNAs which directly target mTOR components, several other miRNAs have been reported to targets that are upstream (mir-22, miR-26, miR-150, miR-193, miR-223, miR-3151) or downstream (miR-29, miR-181) of mTOR signaling, highlighting the importance of the PI3K/Akt/mTOR axis in leukemias." (PMID 30110936, 2018). "MTOR/Akt inhibitors are synergistic with MDM2 inhibitors in inducing apoptosis in leukemias but whether this synergy is autophagy related has not been determined." (PMID 26440941, 2015). "We provide evidence that simultaneous targeting of mTOR complexes with the catalytic mTOR inhibitor OSI-027 and of the p110α subunit of PI3K with the specific inhibitor BYL-719 results in efficient suppression of effector pathways and enhanced induction of apoptosis of leukemia cells." (PMID 25823922, 2015).
leukemia (continued). "There is much evidence to support the critical function of the PI3K/Akt/mTOR signaling pathway in cancer proliferation, tumor genesis and metastasis, and numerous studies have demonstrated that PI3K/Akt/mTOR activity is increased in a variety of tumor cell lines, including leukemia." (PMID 24932295, 2014). "However, results from treatments with compound c and rapamycin reveal that AMPK and mTOR pathways are not involved in cordycepin-reduced β-catenin in leukemia cells." (PMID 24086728, 2013). "Notably, the novel dual PI3K/MTOR inhibitor NVP-BGT226 reveals extraordinary potency to inhibit proliferation as well as to induce apoptosis in the nanomolar range against a broad range of cell lines and ex vivo leukemia samples tested." (PMID 23705826, 2013). "The cytotoxic mechanisms of CYT997 in leukemia cells were also investigated, with a particular focus on its effect on the cyclin-dependent kinase (cdc2) pathway, which regulates the entry of cells into mitosis, and the inhibition of PI3K/Akt/mTOR pathway proteins." (PMID 24137178, 2013). "Moreover, an increased activity of mTOR was observed in the TRIM19−/− hematopoietic stem cells, and the mTOR inhibitor rapamycin substantially rescued the effect of TRIM19 deletion, suggesting that TRIM19 can exert its function in leukemia-initiating cells by inhibiting mTOR activity." (PMID 35205738, 2022). "Therefore, combining POL5551 with newer targeted agents, such as inhibitors of BRD4 or DOT-1L in MLL-R leukemias and phosphoinositide 3-kinase (PI3K) and mTOR inhibitors in hypodiploid ALL and Philadelphia chromosome-like ALL, may improve outcome in these high-risk pediatric leukemias." (PMID 26360610, 2015). "By inhibiting c-Myc expression, MAC has apoptotic effects of K562 leukemia cells without affecting normal blood cells by the stimulation of AMP-activated protein kinase (AMPK) and inhibition of mammalian target of rapamycin (mTOR) phosphorylation." (PMID 36499465, 2022). "While the IL-15/mammalian target of rapamycin (mTOR) and type I interferon (IFN) signaling pathways were constitutively active in NK cells purified from the leukemia murine model, these cells could not respond to stimulation with IL-15, in vitro." (PMID 38254135, 2024). "When the negative mTOR regulator, PTEN, was deleted in murine hematopoietic stem cells (HSCs), PTEN-mutant bone marrow showed rapid depletion of normal HSCs followed by an increased presence of leukemia initiating stem cells (LSCs or CSCs in leukemia) which subsequently resulted in leukemogenesis." (PMID 27826244, 2016). "However, patient-derived primary human AML cells (we used primary AML-PB001F mononuclear blasts obtained from leukaemia patients) do not differ from the two ML cell lines in respect of the easily detectable LPHN1 expression and its upregulation in response to mTOR stimuli (LPS, SCF and anti-Tim-3)." (PMID 27322212, 2016).